RD3 (RD3 regulator of GUCY2D)
Diseases named in the same sentence as RD3 in open-access papers (continued):
Sharing a sentence is not in itself a finding about the gene and the disease.
retinal dystrophies (4 papers, 2013 to 2025). "Here, we report the results of an international study aimed at delineating the clinical and molecular spectrum of RD3 mutations in retinal dystrophies." (PMID 23308101, 2013). "Cohorts of patients affected with various retinal dystrophies screened for RD3 mutations." (PMID 23308101, 2013). "Those conditions are met, for instance, in LCA1 caused by null mutations in RetGC-E (GUCY2D) or LCA12 caused by mutations in RD3, two severe and prevalent inherited retinal dystrophies." (PMID 25058152, 2014). "However, none of the unrelated patients affected by various retinal dystrophies of later-onset and/or severity in our cohort (n = 278) and the other two reported series (n = 907) exhibited disease-causing RD3 mutations." (PMID 23308101, 2013).
tauopathy (4 papers, 2013 to 2024). Neurodegenerative disorders involving deposition of abnormal tau protein isoforms (tau proteins) in neurons and glial cells in the brain. "The immunoreactivity of anti-4R was compared to that of RD4, RD3 and T46 in immunoblotting of Sarkosyl-insoluble tau from tauopathy brains." (PMID 24252707, 2013). "The specificity of the RD3 and RD4 tau antibodies, respectively for the 3R- and 4R-tau isoforms was confirmed in known tauopathy cases." (PMID 25953777, 2015). "The semiquantitative densitometric scanning of protein dot intensity on the dot-blots revealed that similar to ThT fluorescence levels, the intensity of tau aggregates captured by FTA on the blots was significantly higher in tauopathies than in normal controls by both RD4 and RD3 antibodies." (PMID 39609917, 2024).
cone-rod dystrophy (2 papers, 2013 to 2022). Inherited retinal dystrophies that belong to the group of pigmentary retinopathies. "Until now, four LCA genes account for congenital cone-rod dystrophy (LCA type I): GUCY2D, RPGRIP1, CEP290 and RD3 [present study]." (PMID 23308101, 2013).
glioma (2 papers, 2021 to 2025). A benign or malignant brain and spinal cord tumor that arises from glial cells (astrocytes, oligodendrocytes, ependymal cells). "The results showed that in TCGA-GBM (p < 0.001, HR = 0.35) and GSE108474 (p = 0.002, HR = 0.72), patients suffering from glioma with a higher expression of RD3 had a significantly better prognosis than the subgroup with lower expression." (PMID 40234400, 2025). "High DEGs in grade II gliomas included NNMT, MFAP5, APCDD1L-AS1, C7orf57, HP, SERPINA5, and LTF and some highly downregulated DEGs included ABCA4, PDE6A, GRP, RD3, and TMEM72." (PMID 33948562, 2021).
leukemia (2 papers, 2014 to 2015). A malignant (clonal) hematologic disorder, involving hematopoietic stem cells and characterized by the presence of primitive or atypical myeloid or lymphoid cells in the bone marrow and the blood. "Although RD3 has been shown to be associated with the leukemia gene product PML, the crucial role of RD3 in cancer biology has been overlooked." (PMID 26375249, 2015). "The ChIP-seq data showed that the c-Myc oncoprotein bound to the RD3 gene intron 1 region matching the Sp1-binding site-enriched fragment in K562 leukemia cells." (PMID 24586304, 2014).
metastatic tumors (2 papers, 2015 to 2019). "Results from the mouse model identified significant transcriptional/translational loss of RD3 in metastatic tumors and MSDACs." (PMID 31409909, 2019). "Loss of RD3 in metastatic disease was examined using a mouse model of PD and metastatic-site-derived aggressive cells (MSDACs) ex vivo." (PMID 31409909, 2019). "The results from our in vivo studies demonstrated a significant transcriptional and translational loss of RD3 in MSDACs and in metastatic tumors compared with parental SK-N-AS cell and primary xenografts, respectively." (PMID 31409909, 2019). "More importantly, the MSDACs derived from tumors that lack RD3 instantaneously prompt the development of high-risk aggressive metastatic disease." (PMID 26375249, 2015). "Further, our established animal model reflected RD3 loss in aggressive metastatic tumors." (PMID 26375249, 2015). "Nearly all metastatic tumors showed complete RD3 loss, while the non-metastatic tumors did not." (PMID 26375249, 2015). "To further substantiate the RD3 loss in PD, we custom-archived the NM-PX, PD-primary xenografts, PD-metastatic tumors, and reproduced disease with MSDACs in TMA and immunostained for RD3." (PMID 31409909, 2019). "Immunoblotting revealed complete suppression of RD3 in metastatic tumors compared with non-metastatic xenograft controls." (PMID 26375249, 2015).
retinal disease (2 papers, 2013 to 2018). "Thirteen of the differentiated genes are involved in human retinal disease (RetNet database), 11 showed significant increased level of expression, and two are significantly decreased in the rd3 retina when compared to the control." (PMID 23687432, 2013).
Usher syndrome (2 papers, 2017 to 2022). A syndromic diseae characterized by the association of sensorineural deafness (usually congenital) with retinitis pigmentosa and progressive vision loss. "The largest homozygous region was about 42 Mb and contained three IRD-associated genes: CRB1, RD3 (retinal degeneration 3; OMIM# 180040), and USH2A (Usher syndrome type 2A; OMIM# 608400)." (PMID 28460491, 2017).
achromatopsia (1 paper, 2024). Achromatopsia (ACHM) is a rare autosomal recessive retinal disorder characterized by color blindness, nystagmus, photophobia, and severely reduced visual acuity due to the absence or impairment of cone function. "Stationary IRDs constituted 14.2% (3.1% albinism, 4.7% CSNB, 5.4% achromatopsia), variants causative for LCA were assigned to 8.5% (CEP290, GUCY2D, RDH12, CREB1, RPE65, RD3), 6% were annotated in RS1, and 3.1% were annotated in CHM." (PMID 39596324, 2024).
adrenal neuroblastomas (1 paper, 2017). "However, negative RD3 staining in the adrenal medulla observed in this study raises questions regarding its role in normal adrenal embryonal genesis and maturation, in addition to its role in adrenal neuroblastomas." (PMID 29030614, 2017).
diabetes (1 paper, 2022). "Moving on to the tissue expression of the genes, RD3 has the highest median expression in the pituitary and SLC30AL has the highest median expression in the liver; both organs are directly relevant to diabetes pathogenesis and etiology." (PMID 35884374, 2022).
early-onset retinal dystrophy (1 paper, 2025). "The association of RD3 mutations in patients diagnosed with severe early-onset retinal dystrophy brought these 195 amino acids long protein of around 22 kDa into the focus of biomedical research." (PMID 40234400, 2025).
glioblastoma (1 paper, 2025). The most malignant astrocytic tumor (WHO grade IV). "In the present study, we analyzed RD3 expression in glioblastoma in comparison to non-tumor tissue using public databases and qRT-PCR." (PMID 40234400, 2025). "We found that RD3 is downregulated in glioblastoma compared to non-tumor tissues." (PMID 40234400, 2025).
Huntington disease (1 paper, 2015). Huntington disease (HD) is a rare neurodegenerative disorder of the central nervous system characterized by unwanted choreatic movements, behavioral and psychiatric disturbances and dementia. "Huntington’s disease cortical and striatal sections were therefore stained with antibodies specific for 3R- and 4R-tau isoforms (RD3 and RD4, respectively), pathologically phosphorylated tau (AT8 and pS199) and mutant HTT (EM48)." (PMID 25953777, 2015).
hyperopia (1 paper, 2013). A refractive error in which rays of light entering the eye parallel to the optic axis are brought to a focus behind the retina, as a result of the eyeball being too short from front to back. "In LCA type I patients originating from this region with moderate or no hyperopia, RD3 should be screened for mutations first, before GUCY2D, RPGRIP1 and CEP290." (PMID 23308101, 2013). "Refraction may represent a distinctive feature in LCA type I since patients with GUCY2D mutations consistently have high hypermetropia (>+7) with frequent enophthalmia whereas those who harbor RPGRIP1, CEP290 or RD3 mutations present with lower or no hyperopia (, present study)." (PMID 23308101, 2013).
Intellectual disability (1 paper, 2013). "With regard to RD3, it is worth noting that none of the patients reported here whose ages ranged from 2 to 31 had renal failure, neurological symptoms or intellectual disability." (PMID 23308101, 2013).
lung carcinoma (1 paper, 2022). "Among them, we found that RD2, which had a similar structure to RD3, exerted a dramatically different cytotoxic effect on lung cancer cells." (PMID 36500361, 2022).
myopia (1 paper, 2024). "Surprisingly, genes associated with retinal disorders (CLUL1, VSX1, RD3, RS1, and CABP4) and a cone pigment (OPN1LW) were identified in choroid but not retina of progressing chick myopia." (PMID 39028695, 2024).
promyelocytic leukemia (1 paper, 2022). "RD3 is the closest gene to the SNP; this gene encodes a retinal protein that is associated with promyelocytic leukemia-gene product (PML) bodies in the nucleus." (PMID 35884374, 2022).
cancer (6 papers, 2015 to 2026). A tumor composed of atypical neoplastic, often pleomorphic cells that invade other tissues. "RD3 loss, induced by therapy, triggers a reprogramming cascade involving epithelial-mesenchymal transition, pluripotency circuitry, and cancer stem cell enrichment." (PMID 41619263, 2026). "A direct link between the biochemical function of RD3 and cancer might also exist in its ability to regulate guanylate kinase (GUK) activity, an enzyme that is involved in catalyzing the 5’-GMP-to-GDP conversion." (PMID 40234400, 2025). "In addition, identifying the RD3 protein signature in cancer tissues is required to understand its role in cancer biology." (PMID 29030614, 2017). "Though RD3 has been shown to co-localize with the tumor suppressor promyelocytic leukemia (PML) protein, the functional role of this crucial protein in cancer cell biology (or in any other disease systems) has been thus far overlooked." (PMID 26375249, 2015). "Although researchers reported RD3 co-localization with the tumor suppressor PML34, the functional significance of RD3 in cancer biology is unknown." (PMID 31409909, 2019).
tumor (6 papers, 2015 to 2026). "We observed a substantial loss of RD3 in primary and metastatic site tumor tissues from PD animals compared with NM-PX animals." (PMID 31409909, 2019). "TMA quantitation demonstrated a significant (P < 0.001) loss of RD3 in tumor tissues from primary and metastatic sites of mice with PD." (PMID 31409909, 2019). "Although we observed inter-animal, inter-tumor (same animal), and intra-tumor variations, transcriptional loss of RD3 in PD metastasized tumors generally displayed consistent reduction over the manifold of NM-PX controls." (PMID 31409909, 2019). "RD3 positivity directly correlated with T1, while its expression decreased per increased tumor invasive potential, with complete loss in highly invasive T4 tumors." (PMID 26375249, 2015). "To define that the loss of RD3 drives the metastatic potential of NB cells and consequent metastasis, we examined its influence in tumor cell migration and invasion in vitro and in the instigation of aggressive disease with metastasis in vivo." (PMID 26375249, 2015). "Though we observed inter-tumor variations in the mRNA expression levels of RD3, transcriptional loss of RD3 in metastasized tumors generally followed a consistent decrease over the manifold of non-metastatic primary xenograft controls." (PMID 26375249, 2015). "However, any causal relationship between the abnormal regulation of RD3 expression and tumor development is unclear." (PMID 40234400, 2025). "In addition, though we observed inter-tumor variations in the RD3 protein expression levels, comparison between the panel of xenografts to the metastasized tumors revealed a consistent loss of RD3 in metastasized tumors." (PMID 26375249, 2015). "Furthermore, it is unclear whether the loss of RD3 is involved in causing the transformation of cells, or is an epiphenomenon triggered by processes during tumor development." (PMID 40234400, 2025). "Here, we identify retinal degeneration protein 3 (RD3) as a master regulator of NB lineage fidelity and tumor immunogenicity." (PMID 41619263, 2026). "In an animal experiment, it was shown that metastatic tumor cells that lack RD3 form a high number of aggressive metastases." (PMID 40234400, 2025). "To better understand the cellular function of RD3 in the context of tumor development, we performed first functional cell culture studies to clarify a possible involvement of RD3 in cell survival and the cell cycle." (PMID 40234400, 2025). "Next, we explored the alterations in RD3 mRNA in tumor tissues from multiple metastatic sites from different animals and compared the results with those from NM-PX controls." (PMID 31409909, 2019). "In-vivo, RD3 modulates immune cell infiltration, activation, and tumor clearance." (PMID 41619263, 2026). "Nuclear co-localization of RD3 with PML might indicate a role in the regulation of tumor progression, while its cytoplasmic location may be involved in other critical cellular functions." (PMID 29030614, 2017). "However, the underlying mechanisms and why RD3 is downregulated in tumor tissue is not clear so far." (PMID 29515371, 2018). "However, the functional characterization of RD3 in tumor systems has been hampered by the dearth of information on its localization in normal tissue and by the lack of antibodies suitable for staining FFPE tissue, primarily due to the inaccessibility of the epitopes." (PMID 29030614, 2017). "We then performed qRT-PCR for RD3 expression in the GBM tissues from the Evangelisches Krankenhaus cohort and found a significant downregulation of RD3 expression in GBM compared to non-tumor tissue (expression normalized to TBP and HPRT1)." (PMID 40234400, 2025). "RD3 was transcriptionally and translationally regulated in metastatic site-derived aggressive (MSDAC) cells (regardless of CSC status) ex vivo and in tumor manifolds from metastatic sites in reproducible aggressive disease models in vivo." (PMID 26375249, 2015).
retinal disorder (5 papers, 2013 to 2024). Any disease or disorder of the retina. "Deficiency of RD3, a photoreceptor-specific protein located primarily in the inner segment, has been linked to severe retinal disorders in animals and humans." (PMID 33539922, 2021). "Remarkably, the clinical heterogeneity of retinal disorders was highlighted by the identification of RD3–up to now associated only to LCA– as causative of RP, increasing the phenotypes associated to the gene mutations." (PMID 24516651, 2014). "For example, in the primary analysis there were two SNPs associated with mild retinopathy, rs7553035 and rs21661074 near RD3 on chromosome 1." (PMID 23393555, 2013). "Any inhibitory effect of RD3 would therefore reinforce the development of angiogenic dependent retinopathies indicating how critical the expression level of RD3 is." (PMID 36618828, 2022). "Although this combination of in situ and in vitro studies provides only circumstantial evidence for RD3 regulating GC-A and GC-B activities, it might already indicate an impact on the development of retinopathies." (PMID 36618828, 2022).
Mendelian diseases (1 paper, 2018). "The six genes (SCARF2, RD3, COL9A3, FAM161A, RASGRP1 and DLX6) in common between novel contigs, human Mendelian diseases, and hereditary diseases in dogs are significant in known disease phenotypes in humans and animal models." (PMID 30022108, 2018).
RD3 also shares sentences with these, for which no sentence is quoted: retinitis pigmentosa (2 papers); albinism (1); childhood tumor (1); Crohn disease (1); renal failure (1); Usher syndrome type 2A (1); X-linked retinoschisis (1).